GPX1 (glutathione peroxidase 1)
Diseases named in the same sentence as GPX1 in open-access papers (continued):
Sharing a sentence is not in itself a finding about the gene and the disease.
pancreatic ductal adenocarcinoma (2 papers, 2023). An infiltrating adenocarcinoma that arises from the epithelial cells of the pancreas. "Furthermore, in pancreatic ductal adenocarcinoma cells, activation of ROS/AMPK signalling and Gpx-1 degradation may promote the induction of protective autophagy to survive in a glucose-starved tumour microenvironment." (PMID 37242524, 2023).
periodontitis (2 papers, 2023 to 2025). An acute or chronic inflammatory process that affects the tissues that surround and support the teeth. "This study is the first to evaluate the effect of resveratrol administration on gingival tissue mRNA levels and enzyme activities of CAT and GPx1 in a rat experimental periodontitis model simultaneously." (PMID 41395982, 2025). "In this study, NSPT significantly decreased serum GDF-15, hs-CRP, and SP-D and increased GPx-1 in patients with periodontitis." (PMID 37605193, 2023). "In this regard, the present study has achieved significant results with Q-SRP approach with a positive correlation between serum GDF-15, GPx-1, hs-CRP and SP-D with the extent of periodontitis, evaluated through the association with the several periodontal parameters examined." (PMID 37605193, 2023). "However, periodontal treatment performed with Q-SRP determined a better decrease in clinical periodontal parameters and improved GDF-15, GPx-1, hs-CRP and SP-D in patients with periodontitis." (PMID 37605193, 2023). "In this regard, the purpose of the present randomized clinical trial (RCT) was to evaluate the effect of NSPT performed either through Q-SRP or FMD on GDF-15, GPx-1, hs-CRP, and SP-D concentrations in patients with periodontitis at 6-month follow-up after treatment." (PMID 37605193, 2023).
polycystic ovary syndrome (2 papers, 2019 to 2023). A disorder that manifests as multiple cysts on the ovaries. "GPx1 has also been detected in human ovaries, where its polymorphism has been associated with polycystic ovary syndrome, and in the ovaries of aged mice, where it is usually downregulated unless antioxidant supplementation is employed." (PMID 37298244, 2023).
preeclampsia (2 papers, 2016 to 2026). Preeclampsia is a hypertensive disorder of pregnancy that is characterized by new-onset hypertension with proteinuria presenting after 20 weeks of gestation, and depending on mild or severe forms may initially present with severe headache, visual disturbances, and hyperreflexia. "Polymorphisms in other glutathione-related genes (GCLC, GCLM, and GPX1) were consistently associated with increased risks of small-for-gestational-age infants, preeclampsia, and impaired neurodevelopmental outcomes in offspring." (PMID 41718271, 2026). "Several studies have shown that GPX1 enzyme activity and/or mRNA expression is decreased in cases of preeclampsia." (PMID 27923344, 2016). "Although this study did not allow for differences in GPX1 gene or protein levels to be stated with a sufficient degree of confidence, the tendency of reduced antioxidative capacity in retained placentas is interesting in the similarity it bears to preeclampsia." (PMID 27923344, 2016).
psoriasis (2 papers, 2014 to 2024). An autoimmune condition characterized by red, well-delineated plaques with silvery scales that are usually on the extensor surfaces and scalp. "The only study of the GPX1 rs1050450 variant in psoriasis, described as missense Pro200Leu variant, suggested a lack of association between the variant and psoriasis occurrence, but the study was based on a small group of patients and this result awaits confirmation." (PMID 38791044, 2024).
renal fibrosis (2 papers, 2021 to 2022). A final common manifestation of a wide variety of chronic kidney diseases characterized by glomerulosclerosis and tubulointerstitial fibrosis. "Owing to modulation of the GPx-1/NLRP3/Caspase-1 pathway, Se@BSA NPs ameliorated the renal function of IRI-AKI mice in a dose-dependent manner and dramatically arrested the development of renal fibrosis after AKI." (PMID 35664065, 2022).
septic shock (2 papers, 2014 to 2019). Shock caused by infection; frequently caused by gram negative bacteria, although some cases have been caused by other bacteria, viruses, fungi, and protozoa; characterized by fever, chills, tachycardia, tachypnea, and hypotension. "Patients with septic shock manifest pyroglutamic acidosis that correlates with low levels of Glu (except urine Glu/Crea) which can be measured in both serum and urine, and low GPX1/Hb activity." (PMID 31064391, 2019). "The aim of this study was to evaluate the association of erythrocyte selenium concentration with GPx1 activity, Pro198Leu polymorphism and ICU and hospital mortality in septic shock patients." (PMID 24887198, 2014). "Therefore, the objective of this study was to evaluate the association of erythrocyte selenium concentration with glutathione peroxidase (GPx1) activity, GPx1 polymorphisms and with ICU and hospital mortality in septic shock patients." (PMID 24887198, 2014). "Therefore, the objective of this study was to evaluate the association of erythrocyte selenium concentration with GPx1 activity, Pro198Leu polymorphism and with both ICU and hospital mortality in septic shock patients." (PMID 24887198, 2014).
squamous cell carcinoma (2 papers, 2019 to 2021). A carcinoma arising from squamous epithelial cells. "Elevated GPX1 production in squamous cell carcinoma of the oral cavity and the esophagus induced the tumor growth, spread, vascular infiltration, and resistance to Cisplatinum." (PMID 34943522, 2021). "CAFs from squamous cell carcinoma reduced the expression of Smad3 and cJUN to suppress the activity of glutathione peroxidase 1 (GPX1), one key enzyme affecting hydrogen peroxide detoxification." (PMID 31824853, 2019).
status epilepticus (2 papers, 2022 to 2023). Status epilepticus is defined as a continuous seizure lasting more than 30 min, or two or more seizures without full recovery of consciousness between any of them. "However, the profiles of altered GPx1 expression in response to status epilepticus (SE) have not been fully explored." (PMID 35453441, 2022).
ulcerative colitis (2 papers, 2017). An inflammatory bowel disease involving the mucosal surface of the large intestine and rectum. "We found that the AA genotype in GPX1 is associated with ulcerative colitis (OR = 1.93, adjusted P-value = 0.037)." (PMID 28052094, 2017).
urothelial bladder cancer (2 papers, 2021 to 2023). "This study aimed to investigate the association of GPX1 (rs1050450) and SOD2 (rs4880) genetic variants with the urothelial bladder cancer (UBC) risk independently and in combination with smoking." (PMID 36676755, 2023).
Achalasia (1 paper, 2023). A disorder of esophageal motility characterized by the inability of the lower esophageal sphincter to relax during swallowing and by inadequate or lacking peristalsis in the lower half of the body of the esophagus. "Analysis of DEGs showed the upregulations of PPDPF, NENF, and CYBA and downregulations of FOS, DUSP1, and GPX1 in peripheral blood myeloid cells of achalasia." (PMID 37542039, 2023).
acne (1 paper, 2019). An inflammatory process of the sebaceous glands which is characterized by comedones, nodules, papules and/or pustules on the skin. "Compared with the PP genotype subgroup, the L allele carriers (PL+LL genotype) of the GPx1 P198L polymorphism had significantly lower acne grade score (P = 0.004) and tended to have increased waist circumference, average ovarian volume, and MDA levels (P < 0.07) in the patients with PCOS." (PMID 31781040, 2019).
acute liver failure (1 paper, 2024). Rapid deterioration of liver function causing encephalopathy and coagulopathy. "In APAP-induced acute liver failure patients (GSE74000), IKBKG levels decreased, and Nrf2 target genes were also repressed (i.e., HMOX1, PRDX1, TXNRD1, GPX4, GPX1, GCLC, GCLM, and NQO1)." (PMID 38505605, 2024).
Age-related cataract (1 paper, 2024). A type of cataract (opacification of the lens) that forms during the course of aging. "Also, glutathione peroxidase 1, the gene implicated in age-related cataracts, has higher activity on hydrogen peroxide than lipid hydroperoxides, suggesting this is the critical oxidant relevant to age related cataracts." (PMID 39594457, 2024). "This is consistent with Gpx1 but not Cat knockout mice developing age-related cataracts." (PMID 39594457, 2024).
alcohol addiction (1 paper, 2023). "However, to our knowledge, there are no studies that focus on the genetic variability of PON1, SOD2, GPX1, IL1B, IL6, interleukin 6 receptor (IL6R), and miR146a related to the risk of alcohol addiction, and patients’ comorbid psychosymptomatology." (PMID 38275640, 2023). "Thus, we focused on the role of PON1 rs705379, rs705381, rs854560, and rs662, SOD2 rs4880, GPX1 rs1050450, IL1B rs1143623, rs16944, and rs1071676, IL6 rs1800795, IL6R rs2228145, and miR146a rs2910164 in alcohol addiction, and patients’ comorbid psychosymptomatology." (PMID 38275640, 2023).
allergic asthma (1 paper, 2014). A asthma with a basis in a pathological type I hypersensitivity reaction. "Also, a relatively independent effect of the GPX1 P198L gene polymorphism on the risk of allergic asthma was seen." (PMID 24895604, 2014).
amyloid (1 paper, 2013). "Conversely, the dramatically low expression of PGC-1α at 12 months in AD neurons, when we first observe hippocampal amyloid deposits (not shown), is concomitant with the lower levels of SOD1, SOD2 and, particularly, GPX1, compared to WT." (PMID 23374228, 2013).
aneuploidy (1 paper, 2024). Chromosomal disorder consisting of the presence a chromosomal abnormality in which there is an addition or loss of chromosomes within a set. "Considering that ROS can be produced during cytochrome P450 reactions, and steroidogenic granulosa cells are in close proximity to the oocyte, a selenium and GPX1-led defence in granulosa cells may be important for protecting the oocyte and reducing the incidence of aneuploidy." (PMID 38990713, 2024).
Arrhythmia (1 paper, 2023). Any cardiac rhythm other than the normal sinus rhythm. "The risk of dyspnea or arrhythmia development was assessed via multivariate analysis with respect to SOD2, GPX1, GPX3 and Nrf2 genotypes (respectively)." (PMID 37373377, 2023).
brain inflammation (1 paper, 2012). "Sulforaphane enhances cellular antioxidant levels by activation of the Nrf2/ARE pathway, resulting in the upregulation of phase II antioxidant enzymes HO-1 and Gpx1, both of which have been found to have neuroprotective actions during brain inflammation." (PMID 22558388, 2012). "Using semi-quantitative, real-time (RT)-PCR, we probed Nrf2 as well HO-1 and Gpx1, two prototypical Nrf2-transcribed antioxidant proteins that exhibit neuroprotective capabilities during brain inflammation, for changes in mRNA expression." (PMID 22558388, 2012).
brucellosis (1 paper, 2025). Brucellosis is a bacterial infection that spreads from animals to people via unpasteurized dairy products or by exposure to contaminated animal products or infected animals. "Conversely, GPX1, NOS, NQO1 and Nrf2 genes were significantly downregulated in brucellosis-infected does compared to the non-infected." (PMID 39825331, 2025).
cerebral palsy (1 paper, 2019). A group of disorders affecting the development of movement and posture, often accompanied by disturbances of sensation, perception, cognition, and behavior. "The GPx1 P198L, but not CAT C-262T, genetic polymorphism was associated with non-Hodgkin's lymphoma, while the CAT C-262T, but not GPx1 P198L, genetic polymorphism was associated with cerebral palsy after perinatal hypoxic-ischaemic encephalopathy." (PMID 31781040, 2019).
Chagas disease (1 paper, 2015). A parasitic infection caused by Trypanosoma cruzi. "We conclude the therapeutic delivery of D/P vaccine was effective in arresting the chronic parasite persistence and chagasic pathology; and GPx1 over-expression provided additive benefits in reducing the parasite burden, inflammatory/oxidative stress and cardiac remodeling in Chagas disease." (PMID 26075398, 2015).
colon adenocarcinoma (1 paper, 2023). "In conclusion, Gpx-1 was identified as a protein associated with decreased 5-year survival in patients with colon adenocarcinoma based on the results of the Cox regression model." (PMID 37242524, 2023). "The prognostic significance of Gpx-1 expression in colon adenocarcinoma patients was analysed in relation to 5-year survival." (PMID 37242524, 2023). "The high immunohistochemical expression of Gpx-1 is correlated with poor prognosis of colon adenocarcinoma patients." (PMID 37242524, 2023). "In our cohort of patients, the grade of tumour differentiation and Gpx-1 expression were found to be independent prognostic factors for 5-year survival in patients with colon adenocarcinoma." (PMID 37242524, 2023). "Among the study cohort, 74 (51.75%) colon adenocarcinoma samples demonstrated the high immunohistochemical expression of Gpx-1 protein, whereas 69 (48.25%) showed low immunoreactivity." (PMID 37242524, 2023). "In our cohort of patients, approximately 78% of the colon adenocarcinoma specimens showed a high level of Gpx-1 protein expression, while a low level of immunoreactivity was found in only 22% of the cases." (PMID 37242524, 2023). "In samples of colon adenocarcinoma, the positive immunohistochemical reaction indicating the presence of Gpx-1 protein was observed in the cytoplasm and nuclei of both the cancer cells and stromal cells." (PMID 37242524, 2023). "It should be noted that our study is the first to evaluate the clinical application of the expression of Gpx-1, in particular in relation to the 5-year survival rate in patients with colon adenocarcinoma from Europe." (PMID 37242524, 2023). "TEM studies using the immunogold labelling method confirmed that Gpx-1 in colon adenocarcinoma cells showed cytoplasmic expression." (PMID 37242524, 2023). "Notably, our study is the first to demonstrate immunohistochemical expression of Gpx-1 in colon adenocarcinoma tissue in patients from European populations." (PMID 37242524, 2023). "Against this background, we investigated the Gpx-1 protein expression in a population of European (Polish) patients with colon adenocarcinoma in the absence of any therapy prior to radical surgery." (PMID 37242524, 2023). "Therefore, our aim was to investigate the expression of Gpx-1 protein in a population of Polish patients with colon adenocarcinoma in the absence of any therapy prior to radical surgery." (PMID 37242524, 2023).
colorectal adenocarcinoma (1 paper, 2023). The most common type of colorectal carcinoma. "The localisation of the Gpx-1 protein at the cellular level in colorectal adenocarcinoma samples was demonstrated using an immunogold labelling method." (PMID 37242524, 2023).
coronary artery calcification (1 paper, 2007). Calcification of the coronary artery, used as a measure of coronary atherosclerosis, a risk factor for myocardial infarction. "This study revealed a genetic association between the presence of the Pro197Leu variant of the GPx-1 gene with MSCT-detected coronary artery calcification." (PMID 17825092, 2007).
cutaneous melanoma (1 paper, 2022). A primary melanoma arising from atypical melanocytes in the skin. "SELENBP1 is identified to be downregulated in cutaneous melanoma influenced by glutathione peroxidase 1 (GPX1) to regulate proliferation and tumor microenvironment." (PMID 36386843, 2022).
cystic fibrosis (1 paper, 2018). Autosomal recessive disorder caused by pathogenic variants in the CFTR gene (cystic fibrosis transmembrane conductance regulator), which encodes a chloride and bicarbonate channel expressed in epithelial cells, and follow the diagnosis criteria. "Furthermore, it was shown that the GSH level and GPx-1 activity in sputum were decreased in adult patients with cystic fibrosis." (PMID 30186615, 2018).
dengue (1 paper, 2023). "In children and adults, gene ontology biological process (GOBP) terms calculated (p adj <= 0.05) using markers reflected increased interferon signaling in primary dengue, driven by increased expression of genes including IFITM2 and IRF4 in adults and GPX1 and TCEB2 in children." (PMID 37638019, 2023).
diabetic retinopathy (1 paper, 2024). "S-adenosylmethionine is the main methyl donor used by DNA methyltransferases (Dnmts) for DNA methylation, but the role of hyperhomocystemenia in GPx1 promoter DNA methylation in diabetic retinopathy is not elucidated." (PMID 38539790, 2024).
endometritis (1 paper, 2025). An acute or chronic, usually bacterial infectious process affecting the endometrium. "Furthermore, the RT-qPCR evaluation of the antioxidant-stress-related enzymes (CAT, GPx1, SOD) at the mRNA level indicated that the endometritis group also displayed a marked increase in the mRNA expressions of CAT, GPx1, and SOD compared to the healthy group." (PMID 40646747, 2025).
epileptic seizures (1 paper, 2022). "Therefore, our findings highlight the importance of the preservation/maintenance of GSH levels in the protection of neurons and astrocytes from detrimental stress induced by SE and epileptic seizures, thereby increasing GPx1 expression." (PMID 35453441, 2022).
esophageal squamous cell carcinoma (1 paper, 2019). Esophageal squamous cell carcinoma (ESCC) is a type of esophageal carcinoma (EC) that can affect any part of the esophagus, but is usually located in the upper or middle third. "Increased expression of GPX1 promotes cell proliferation, migration, invasion, and cisplatin-resistance in esophageal squamous cell carcinoma." (PMID 31844035, 2019).
familial hypercholesterolemia (1 paper, 2024). An inheritable form of hyperlipidemia, in which there are excess lipids in the blood. "Moreover, an oral fat load could induce upregulation of the GPx1 and GPx4 genes at 4 h in both familial hypercholesterolemia patients and normolipidemic volunteers." (PMID 39691690, 2024).
female infertility (1 paper, 2022). Diminished or absent ability of a female to achieve conception. "GPX1 198Pro > Leu and CAT-262C > T are most frequently associated with female infertility." (PMID 36013572, 2022).
fibromyalgia (1 paper, 2022). A chronic disorder of unknown etiology characterized by pain, stiffness, and tenderness in the muscles of neck, shoulders, back, hips, arms, and legs. "Elevated SOD activity paired with unchanged GPX1 activity have also been reported in fibromyalgia patients, a pain syndrome associated with increased lipid peroxidation." (PMID 35906211, 2022).
fibrosis (1 paper, 2024). the formation of excess fibrous connective tissue in an organ or tissue in a reparative or reactive process. "The gene expressions of superoxide dismutase (SOD1; SOD2) and glutathione peroxidase (GPx1) were evaluated using real-time PCR in advanced fibrosis (AF: F3F4) in patients with PBC." (PMID 38671835, 2024).
follicular thyroid cancer (1 paper, 2024). "These authors observed a reduction in Sod2-to-Gpx1 and Sod2-to-catalase ratios in DRP-TpoKO mice (follicular thyroid cancer model), indicating an inability to scavenge ROS." (PMID 39125641, 2024).
Friedreich ataxia (1 paper, 2024). An inherited condition that affects the nervous system and causes movement problems. "Furthermore, GPX1 activity may be used as a biomarker for Friedreich’s ataxia, a fatal neurodegenerative disease." (PMID 39273702, 2024).